TNF (tumor necrosis factor)
Diseases named in the same sentence as TNF in open-access papers (continued):
Sharing a sentence is not in itself a finding about the gene and the disease.
multiple sclerosis (continued). "Higher production of proinflammatory TNFα and susceptibility to multiple sclerosis is also associated with some genetic variants in the NF-κB signaling cascade, such as variants proximal to NFκB1 and in an intron of TNFRSF1A (TNFR1), which leads to higher NF-κB signaling after stimulation with TNFα." (PMID 33271810, 2020). "Additionally, increased levels of miR-132-5p in human B cells were associated with the onset of multiple sclerosis (MS) associated with a severe increase of proinflammatory factors such as TNF and lymphotoxin." (PMID 31940779, 2020). "TNF-α is a proinflammatory molecule with antitumor and antiviral effects and is thought to play a role in the pathogenesis of acquired immune deficiency syndrome and multiple sclerosis." (PMID 31253154, 2019). "However, in other autoimmune disorders, such as multiple sclerosis and lupus nephritis, TNFα deficiency or blockade can exacerbate inflammation and precipitate disease flare." (PMID 30305177, 2018). "Of note, EZH2-positive cells both in CD4+ and CD8+ T cells may have pathogenic potential through the secretion of TNF-α, a pro-inflammatory cytokine involved in the pathogenesis of multiple sclerosis." (PMID 30367633, 2018). "Research is also warranted in other neurologic conditions, such as multiple sclerosis, Parkinson's disease, amyotrophic lateral sclerosis, and others, seeking the degree to which TNF alpha related inflammation may also play a causative role in those conditions." (PMID 26664821, 2015). "A placebo-controlled study involving human patients with multiple sclerosis demonstrated that coenzyme Q10 supplementation significantly decreased TNF-α and IL-6 levels compared to the placebo group." (PMID 40520426, 2025). "The rationale for TNFR2 agonism to treat multiple sclerosis stems from several lines of evidence, starting with the importance of TNF in MS pathogenesis." (PMID 40869160, 2025). "Cognitive behavioral therapy and psychodynamic therapy have been shown to reduce TNF-α in depressed patients, and cognitive behavioral stress management led to reduction in IL-12 levels in multiple sclerosis patients." (PMID 40517143, 2025). "The major importance of TNF-α in multiple sclerosis has led to the development of targeted therapies aimed at modulating TNF-α activity." (PMID 38999258, 2024). "For example, the elevated TNF-α levels at the lesion site were observed in multiple sclerosis and Parkinson’s disease patients at autopsy, and TNF-α was also significantly up-regulated in AD patients and AD model mice." (PMID 37307837, 2024). "Similar to our findings, TNF treatment of microglial cells in vitro and the excess of TNF in the brains of multiple sclerosis patients or the respective mouse models reduced catalase levels, resulting in oxidative stress." (PMID 38339126, 2024). "In patients with multiple sclerosis, circulating TNF-α mRNA and TNF-α and interferon-γ protein levels increased." (PMID 38724532, 2024). "Conversely, the use of TNF-α inhibitors is contraindicated in patients with a history of malignancy or multiple sclerosis." (PMID 39240834, 2024). "On the other hand, TNFα can exert a neurotoxic effect, as demonstrated in AD and Parkinson’s disease (PD), epilepsy, multiple sclerosis (MS), as well as chronic pain, ischemic and traumatic brain injury, and infectious diseases, among others." (PMID 39456170, 2024). "As an example, the TNF system plays a role in both the pathophysiology of RA and multiple sclerosis through the overproduction of proinflammatory cytokines." (PMID 39403668, 2024). "Multiple Sclerosis (MS) is an auto-inflammatory disease based on the increase of TNF-a and the decrease of TGF-b." (PMID 39166055, 2024). "TNF-dependent synaptotoxicity contributes to the neuronal damage occurring in patients with Multiple Sclerosis (pwMS) and its mouse model Experimental Autoimmune Encephalomyelitis (EAE)." (PMID 37021418, 2023).
multiple sclerosis (continued). "Contrary to initial expectations, anti-TNF-α therapy has been found to have detrimental effects in multiple sclerosis." (PMID 37483590, 2023). "Bacterial species that were more abundant in cases with disease-active treatment-naïve multiple sclerosis were positively linked to a group of plasma cytokines including IL-22, IL-17A, IFN-β, IL-33, and TNF-α." (PMID 36604748, 2023). "Increased levels of TNFα, IL-6 and IL-10 were evident in the blood of an LPS-treated animal model of multiple sclerosis." (PMID 37999377, 2023). "A second example of pathological alterations induced by enhanced TNFα levels via the astrocyte pathway comes from our studies in a murine model of multiple sclerosis, the experimental autoimmune encephalitis (EAE) model." (PMID 34904753, 2022). "For instance, in the case of multiple sclerosis, the release of TNF-α from activated myeloid cells contributes to GSDMD upregulation, which further promotes pyroptosis in oligodendrocytes and demyelination." (PMID 35350377, 2022). "We found that inflammation elements and pathways, extracellular matrix organization, adipogenesis, TGF-B signaling and activation, JAK/STAT signaling, and TNF/stress oxidative pathway with principal roles are involved in multiple sclerosis development." (PMID 35676653, 2022). "Many of these cytokines such as interleukin 6, IL-2 T cell growth factor, tumor necrosis factor alpha (TNF-α) are also involved in the regulation of signaling pathways in the development of multiple sclerosis." (PMID 36232592, 2022). "For instance, in multiple sclerosis (MS), astrocytes secrete proinflammatory factors such as the tumor necrosis factor (TNF)-α, interleukin (IL)-1β, and IL-6, negatively affecting OPCs differentiation." (PMID 35740258, 2022). "Conversely, the same TNF-α inhibitors are contraindicated in patients with a history of malignancy and multiple sclerosis." (PMID 34816130, 2021). "In those studies, the levels of TNF-alpha and alpha-1 antichymotrypsin were also elevated in the CSF of parkinsonian patients and multiple sclerosis patients, respectively." (PMID 34811435, 2021). "The reduced function of TNF and its major proinflammatory receptor TNFR1 was a risk factor for the development of multiple sclerosis." (PMID 34306139, 2021). "TNF is one of the main inflammatory mediators involved in several pathological conditions, including chronic inflammatory diseases such as multiple sclerosis (MS)." (PMID 34359880, 2021). "Sustained TNF expression has a key role in the target organ pathology of several chronic inflammatory diseases, such as multiple sclerosis." (PMID 34359880, 2021). "Further analysis of TNFα is crucial because this cytokine holds a central position in relation to a plethora of CNS conditions, including CNS-TB, autism and multiple sclerosis." (PMID 32225060, 2020). "IL-22 receptor was detected in human astrocytes of both healthy controls and multiple sclerosis patients, and IL-22 treatment reduced TNF-α-induced apoptosis of astrocytes." (PMID 32843067, 2020). "In patients with multiple sclerosis a 12-week trial with probiotics led to a significantly improved gene expression of IL-8 and TNF-α." (PMID 32858844, 2020). "Further, clinical evaluation of anti-TNF therapy in multiple sclerosis failed and anti-TNF therapy of juvenile rheumatoid arthritis resulted in development of MS-like exacerbations and demyelinating lesions in some patients." (PMID 32528961, 2020). "The expression levels of TPGRL1 and TYROBP and IL-8 and TNF-α increased for diabetic patients, whereas TYROBP and USP16 and IL-6, IL-8, CSF2, and TNF-α increased for multiple sclerosis patients." (PMID 32517215, 2020). "The expression level can be up-regulated in response to a number of different insults to the CNS, such as treated with IFN-γ, TNF-a, and lipopolysaccharide (LPS) in vitro, during acute phase of infection or at multiple sclerosis lesions." (PMID 31864410, 2019).
multiple sclerosis (continued). "Consistently, the expression of inflammatory cytokines such as IL-8 and TNF-α in diabetic patients and IL-6, IL-8, CSF2 and TNF-α in multiple sclerosis patients increased." (PMID 31294790, 2019). "Second, we assess the astrocytic response to IL-1β, TNF-α, and IL-6, all cytokines important in neuroinflammation, such as multiple sclerosis." (PMID 30409508, 2018). "DYSF is induced in vitro by TNF-alpha and has also been shown to be up-regulated in the blood vessels of patients with multiple sclerosis representing increased vascularinflammation and a disturbed blood–brain barrier." (PMID 29530068, 2018). "TNF-α levels in blood samples from a multiple sclerosis mouse model decreased significantly after dasatinib therapy." (PMID 30687331, 2018). "Initial studies in experimental autoimmune encephalomyelitis (EAE) animal models of multiple sclerosis (MS) showed beneficial effects of TNF-α blockers." (PMID 28337644, 2017). "Intriguingly, some patients receiving anti-TNF-α therapy who had multiple sclerosis as a comorbidity developed exacerbation of their neurological disease, suggesting a proinflammatory consequence of generic TNF-α blockade in certain circumstances." (PMID 27747245, 2016). "GM-CSF, IL6, and TNFα are well known as proinflammatory cytokines and are upregulated in various kinds of white matter diseases, including multiple sclerosis (MS) and neuromyelitis optica (NMO)." (PMID 27402089, 2016). "Tumor necrosis factor (TNF) has pleiotropic functions during both the demyelinating autoimmune disease multiple sclerosis (MS) and its murine model experimental autoimmune encephalomyelitis (EAE)." (PMID 26906225, 2016). "The aim of this study was to evaluate ENA 78, IL-1β and TNF-α plasma levels in multiple sclerosis (MS) and neuromyelitis optica (NMO) patients." (PMID 27401736, 2016). "In contrast infiltration of T cells occurs in multiple sclerosis and PD, and levels of IL-1β, IL-6 and TNF-α are elevated in the cerebrospinal fluid of PD patients." (PMID 26634899, 2015). "There is a marked increase in expression of TNF in active multiple sclerosis (MS), and a correlation exists between cerebrospinal fluid levels of TNF and the severity and progression of disease." (PMID 24683506, 2014). "Various proinflammatory and Th1-dependent cytokines, such as IL-12, IFN-γ and TNF-α play a role in the pathogenesis of multiple sclerosis by promoting myelin sheath injury." (PMID 24852423, 2014). "Since anti-tumor necrosis factor therapy increases exacerbations of multiple sclerosis, complications of demyelinating diseases contraindicate anti-tumor necrosis factor therapy." (PMID 25216562, 2014). "HSV-1 encephalitis has also been reported in patients taking natalizumab for multiple sclerosis, and patients taking tumor necrosis factor-alpha inhibitors." (PMID 26237609, 2014). "CCR2 on monocytes is downregulated with most inflammatory conditions in vitro and in vivo, including TNF-α or LPS treatment as well as in atherosclerotic plaques and multiple sclerosis lesions." (PMID 23922698, 2013). "TNF-α is one of the most abundant cytokines produced in many inflammatory and autoimmune conditions such as multiple sclerosis, chronic hepatitis C, or neurodegenerative diseases." (PMID 23533448, 2013). "Evidence from an animal study on multiple sclerosis demonstrates that BDNF decreases the expression of TNF-α." (PMID 23912236, 2013). "Among the major adverse effects of TNF-α inhibitors, demyelinating disease, multiple sclerosis, and acute transverse myelitis have been reported in adults." (PMID 22937436, 2011). "The HERV-W syncytin-1 exerted its inflammatory effects by induction of proinflammatory mediators, such as IL-1β, IL-6, IL-12, iNOS, and TNF-α, leading to neuron inflammation in multiple sclerosis patients." (PMID 21772664, 2011).
multiple sclerosis (continued). "Elevated levels of TNF-α and TNF-α medicated signaling pathways are evident in a large number of neurological disorders including multiple sclerosis (MS), AD, Parkinson's disease (PD), and ALS." (PMID 20950451, 2010). "No clinical efficacy or worsening of the symptoms has been reported in some Multiple Sclerosis patients treated with TNF-α inhibitors." (PMID 19490629, 2009). "The roles of cytokines, such as IFN-γ, TNF-α, IL-1β and IL-6, expressed in inflammatory diseases such as multiple sclerosis are complex." (PMID 18793322, 2008). "The TNF-α system has also been shown to be involved in the development of other brain diseases such as multiple sclerosis (MS)." (PMID 19506720, 2008). "In a murine model of T‐cell activation, Acthar reduced the activation of CD4+ and CD8+ T cells as well as the production of cytokines (interleukin‐2, interferon γ, and TNFα), which are involved in inflammatory immune responses in autoimmune disorders, such as multiple sclerosis." (PMID 40223398, 2025). "Western blotting analysis revealed significantly elevated protein expression of the pro-inflammatory cytokine TNF-α (a critical factor in multiple sclerosis with myelinolytic effects) and reduced expression of myelin-associated proteins MBP and MAG in Cuprizone-fed mice compared to controls." (PMID 40563355, 2025). "Associations were found between change scores in (i) Six Spot Step Test and Interleukin (IL)-2, IL-8, and IL-17 levels; (ii) timed 25-foot walk and interferon-γ, IL-2, IL-8, TNF-α, and neurofilament light levels, and (iii) 12-Item Multiple Sclerosis Walking Scale and IL-17 levels." (PMID 38338871, 2024). "As a result, TNF-α inhibitors can be successfully used as a therapy against autoimmune inflammatory diseases, where they are more effective than disease-modifying drugs but proved detrimental against neurodegenerative disorders such as multiple sclerosis." (PMID 39459490, 2024). "However, the use of anti-TNF-α therapies in multiple sclerosis is still under investigation, and the efficacy and safety continue to be evaluated." (PMID 38999258, 2024). "One study conducted in 2011 in 10 patients revealed the development of demyelination events as a result of TNF-α inhibitor therapy with a clear distinction from sporadic multiple sclerosis; most symptoms occurred within one year from the beginning of the therapy." (PMID 39336450, 2024). "This means that TNF-α may play a dual role in multiple sclerosis, contributing both to the progression of the disease and to its healing mechanisms." (PMID 38999258, 2024). "Indeed, the use of TNF-α inhibitors in patients with multiple sclerosis has showed a worsening of the disease." (PMID 36836166, 2023). "Moreover, the combination of these cannabinoids decreased the expression of TNF-α and increased Brain-derived neurotrophic factor in multiple sclerosis in vivo model." (PMID 37147420, 2023). "In multiple sclerosis (MS), TNF-α blockade can lead to paradoxical worsening of the disease." (PMID 37483590, 2023). "Based on enrichment and data mining, we found that inflammation elements, extracellular matrix organization, adipogenesis, TGF-B signaling and activation, JAK/STAT signaling, and TNF/stress oxidative pathway with principal roles are involved in multiple sclerosis development." (PMID 35676653, 2022). "The use of TNF blockers is not applied in multiple sclerosis treatment because of its association with demyelination." (PMID 36428505, 2022). "In contrast to our findings, one RCT study indicated that 0.5 mL/kg/day sesame oil consumption along with interferon beta-1a decreased TNF-α measured in supernatants of peripheral blood mononuclear cells in patients with multiple sclerosis compared to patients who only received interferon beta-1a." (PMID 34760018, 2021).
multiple sclerosis (continued). "This novel transcript directs the expression of a soluble form of TNFR1, which is capable of TNFα antagonism and might be responsible for worsening multiple sclerosis upon anti-TNF therapy." (PMID 33603056, 2021). "Importantly, clinical evaluation of an anti-TNF therapy in multiple sclerosis (MS) failed and anti-TNF therapy of juvenile rheumatoid arthritis resulted in development of MS-like exacerbations and demyelinating lesions in some patients." (PMID 34305946, 2021). "Conversely, TNF-α inhibitors are absolutely contraindicated in the case of multiple sclerosis." (PMID 34829740, 2021). "An imbalance of TNF signalling in the inflammatory milieu generated by meningeal immune cell infiltrates in the subarachnoid space in multiple sclerosis (MS), and its animal model may lead to increased cortical pathology." (PMID 34359880, 2021). "However therapeutic attempts to improve MS outcomes through inhibition of TNF signaling proved to instead worsen disease (The Lenercept Multiple Sclerosis Study Group and The University of British Columbia MS/MRI Analysis Group, 1999)." (PMID 33473245, 2020). "TNFα signal transduction in lymphocytes is altered in multiple sclerosis." (PMID 33271810, 2020). "To further our understanding of microglia phenotypic changes under inflammatory conditions, we present here preliminary data describing the microglia transcriptome after exposure to either TNF or GM-CSF, cytokines found in the multiple sclerosis demyelinating milieu." (PMID 33473245, 2020). "Moreover, it has been shown that the pro-inflammatory cytokine tumor necrosis factor-α (TNF-α) signals through astrocytes to alter synaptic transmission and impair cognition in a mouse model of multiple sclerosis." (PMID 30249283, 2018). "The inhibitory effects of GYY4137 on NO and TNF production may be beneficial in neuroimmunological diseases such as multiple sclerosis and neurodegenerative disorders, as these molecules are implicated as important mediators in their pathogenesis." (PMID 30441775, 2018). "TNFα may also exert protective effects against ischemia, multiple sclerosis, excitotoxic damage, and oxidative stress." (PMID 29464573, 2018). "Results showed that: 1) the expression of IL-10 mRNA was increased in PBMCs of HC alone compared to patients with a diagnosis of PP, SP, RR and BE multiple sclerosis; and 2) TNFα mRNA was augmented only in PBMC of PPMS patients compared to SPMS, RRMS, BEMS and HC." (PMID 27412504, 2016). "Furthermore, a clinical study demonstrated that fish oil decreased serum levels of TNF-alpha, IL-1beta, IL-6, and nitric oxide metabolites in multiple sclerosis patients treated with IFN-1beta." (PMID 27313881, 2016). "There is also evidence that IL-6 and TNF-α could act as mediators in the incidence of depressive symptoms in patients with some other diseases, such as coronary artery disease or multiple sclerosis." (PMID 27918465, 2016). "In addition, the benefits of pirfenidone in multiple sclerosis suggest a possible role for TNF alpha in the etiology of multiple sclerosis, as well as potential benefit of other TNF inhibiting agents in its treatment." (PMID 26664821, 2015). "The amino-terminal domain of TyrRS (1 nM) has been reported to induce PMN migration, and human myelin basic protein (10–30 μg/ml) has been reported to induce a dose-dependent release of interferon-γ, TNF-α and IL-10 from the mononuclear cells of patients with multiple sclerosis." (PMID 25915936, 2015). "Given the anti-TNF activity of pirfenidone and its apparent efficacy and safety in multiple sclerosis, as well as its ability to cross the blood brain barrier, it may be candidate drug to study in an AD population." (PMID 26664821, 2015). "Furthermore, we discuss these results in the frame of previous disappointing results from anti-TNF-α clinical trials against Multiple Sclerosis, another neurodegenerative disease with a clear neuroinflammatory component." (PMID 23641196, 2013).